KSR2 (kinase suppressor of ras 2)
Description:
Location-regulated scaffold connecting MEK to RAF. Has very low protein kinase activity and can phosphorylate MAP2K1 at several Ser and Thr residues with very low efficiency (in vitro). Acts as MAP2K1/MEK1-dependent allosteric activator of BRAF; upon binding to MAP2K1/MEK1, dimerizes with BRAF and promotes BRAF-mediated phosphorylation of MAP2K1/MEK1. Interaction with BRAF enhances KSR2-mediated phosphorylation of MAP2K1 (in vitro). Blocks MAP3K8 kinase activity and MAP3K8-mediated signaling. Acts as a negative regulator of MAP3K3-mediated activation of ERK, JNK and NF-kappa-B pathways, inhibiting MAP3K3-mediated interleukin-8 production.
Synonyms: FLJ25965
Tractability: Small molecule: a structure with a bound ligand is known; a high-quality ligand is known; it has a high-quality binding pocket; it belongs to a druggable protein family. Antibody: UniProt places it where antibodies can reach, with medium confidence; its Gene Ontology location is reachable by antibodies, with medium confidence. PROTAC: ubiquitination databases record sites on it; its protein half-life has been measured; a small molecule that binds it is known.
Target class: Enzyme; Transferase
Gene: Protein-coding gene on chromosome 12 (117,453,012 to 117,968,990, reverse strand). Ensembl gene ENSG00000171435.
Subcellular location: Cytoplasm; Membrane
Pathways (Reactome):
Disease: Paradoxical activation of RAF signaling by kinase inactive BRAF; Signaling by BRAF and RAF1 fusions; Signaling by RAF1 mutants; Signaling by high-kinase activity BRAF mutants; Signaling by moderate kinase activity BRAF mutants; Signaling downstream of RAS mutants
Signal Transduction: MAP2K and MAPK activation
Gene Ontology:
Molecular function: protein binding; protein serine kinase activity; protein serine/threonine kinase activity; ATP binding; MAP-kinase scaffold activity; mitogen-activated protein kinase kinase binding; protein kinase activity
Biological process: calcium-mediated signaling; positive regulation of cold-induced thermogenesis; Ras protein signal transduction; MAPK cascade
Cellular component: cytosol; plasma membrane; cytoplasm; membrane
Genetic constraint (gnomAD): Loss-of-function variants: 23 observed, 102.34 expected, observed/expected ratio (o/e) 0.22, 90% interval 0.16 to 0.32. The upper end of that interval is the gene's LOEUF score, 0.32, which puts it in group 1 of 6, group 1 being the genes least tolerant of losing a copy. Missense variants: 873 observed, 1,283.2 expected, observed/expected ratio (o/e) 0.68, 90% interval 0.64 to 0.72. Synonymous variants: 477 observed, 517.42 expected, observed/expected ratio (o/e) 0.92, 90% interval 0.85 to 0.99.
Homologues: Orthologues: chimpanzee KSR2 (100% identical), macaque KSR2 (99% identical), pig KSR2 (99% identical), dog KSR2 (99% identical), rabbit KSR2 (98% identical), rat Ksr2 (97% identical), mouse Ksr2 (97% identical), guinea pig KSR2 (96% identical), tropical clawed frog ksr2 (89% identical), zebrafish ksr2 (82% identical). Paralogues in human: KSR1 (48% identical), BRAF (15% identical), TNNI3K (14% identical), RAF1 (14% identical), LRRK2 (14% identical), ARAF (14% identical), LIMK1 (12% identical), LIMK2 (11% identical), MAP3K10 (11% identical), MAP3K9 (11% identical), MAP3K13 (11% identical), MAP3K21 (11% identical), and 11 more.
Diseases named in the same sentence as KSR2 in open-access papers:
KSR2 is named in the same sentence as 32 diseases in open-access papers, as found by Europe PMC text mining. Sharing a sentence is not in itself a finding about the gene and the disease. The quoted sentences say what the papers report.
Obesity (35 papers, 2013 to 2026). Accumulation of substantial excess body fat. "For example, CHST11 is a reported target of PPAR-gamma, involved in lipid accumulation in adipocytes, while KSR2 regulates energy intake and expenditure and has been implicated in obesity and IR." (PMID 40699860, 2025). "Variants of the KSR2 gene are correlated with excessive daytime sleepiness, which is connected to obesity due to disturbances in energy homeostasis." (PMID 40024983, 2025). "Given the association of Ksr2 with obesity,drugs capable of upregulating its expression are prioritized." (PMID 40062973, 2025). "Subsequent research, including various studies and case reports, has further explored the relationship between KSR2 gene variants and obesity or related metabolic conditions in both human and animal models." (PMID 39202327, 2024). "KSR2 is an important regulator of energy intake and mutation in this gene have been linked to obesity and insulin resistance." (PMID 38532495, 2024). "The study concludes that these four KSR2 variants are associated with monogenic obesity, with an autosomal dominant inheritance pattern." (PMID 39202327, 2024). "This study conducted an analysis of nine Arab patients in Qatar with early-onset obesity with variants in the KSR2 gene." (PMID 39202327, 2024). "This study investigated KSR2 variants in 9 pediatric patients with severe early-onset obesity in Qatar using whole genome sequencing among a cohort of 240 individuals." (PMID 39202327, 2024). "In this study, we have identified four genetic variants in the KSR2 gene that are linked to early-onset monogenic obesity in our cohort of seven Qatari, one Saudi, and one Qatari–Saudi patients." (PMID 39202327, 2024). "The kinase suppressor of Ras 2 (KSR2) gene is associated with monogenic obesity, and loss-of-function variants in KSR2 have been identified in individuals with severe early-onset obesity." (PMID 39202327, 2024). "The reported obesity cases linked to KSR2 variants are relatively rare and exhibit an autosomal dominant pattern of inheritance." (PMID 39202327, 2024). "This study provides new insights into the role of KSR2 variants in the development of monogenic obesity in the understudied Qatari population and paves the way for further research in the area." (PMID 39202327, 2024). "KSR2 mutations lead to obesity due to hyperphagia, a reduced metabolic rate, and severe insulin resistance." (PMID 37374323, 2023). "A new study identified several mutations in KSR2 that are linked to the development of early-onset obesity and severe insulin resistance." (PMID 35468812, 2022). "In contrast, one third of Ksr2‐deficient mice display perinatal mortality and the surviving animals develop obesity and insulin‐resistance." (PMID 35313064, 2022). "Although there are hundreds of mouse genes reported to lead to obesity when disrupted, Ksr2 gene deletion is associated with a profound obese phenotype and lethality at a young age." (PMID 36342465, 2022). "In humans, KSR2 variants have been demonstrated to play a key role in energy homeostasis and obesity." (PMID 36263427, 2022). "Humans with certain genetic polymorphisms at the kinase suppressor of ras2 (KSR2) locus develop severe early-onset obesity and type 2 diabetes." (PMID 36342465, 2022). "Consistent with a selective role of KSR2 in controlling energy expenditure, KSR2 mutations associated with obesity and insulin resistance have been found in humans." (PMID 35313064, 2022). "We found that all of our participants with AMD were heterozygous for KSR2 rs895471 (A > G), and variation in KSR2 has been associated with obesity, insulin resistance, and impaired cellular fuel oxidation." (PMID 34299682, 2021). "Variants within KSR2 have been shown to play an important role in energy homeostasis and obesity in humans." (PMID 28463982, 2017). "Humans with KSR2 mutations exhibit childhood hyperphagia, early-onset obesity, reduced metabolic rate, and severe insulin resistance." (PMID 27561547, 2016).
Obesity (continued). "KSR2 presents an enticing therapeutic target, as mutations (some of which locate to the PKD) in KSR2 affect energy balance and are associated with numerous diseases, like obesity and related metabolic problems." (PMID 26589967, 2015). "By using a whole-exome sequencing strategy, KSR2 loss-of-function mutations were identified in humans and were associated with hyperphagia, early-onset obesity, low heart rate, reduced basal metabolic rate and severe insulin resistance." (PMID 25825681, 2015). "Diet does not reverse the underlying metabolic defects caused by disruption of KSR2, however, as ad libitum feeding of diet‐restricted ksr2−/− mice restores obesity and glucose intolerance." (PMID 24997067, 2014). "Mutations in KSR-2 were recently described to be associated with obesity and insulin resistance in human." (PMID 24829611, 2014). "Given the similarities in metabolic characteristics between the C57BL/6 ksr2−/− model and humans bearing KSR2 mutations, we propose the broad utility of ksr2−/− mice to the study, treatment, and prevention of human obesity and obesity‐related disorders." (PMID 24997067, 2014). "Some KSR2 mutations in individuals with early onset obesity disrupt ERK activation or impair interaction of the scaffold with AMPK." (PMID 24997067, 2014). "The phenotype of C57BL/6 ksr2−/− mice, including obesity and obesity‐related dysregulation of glucose homeostasis, recapitulates that of humans with KSR2 mutations." (PMID 24997067, 2014). "Obesity in KSR2−/− mice is linked to AMPK dependent glucose uptake and fatty acid oxidation, as KSR2 interacts with AMPK and modulates its activity." (PMID 24829611, 2014). "In this study, we linked the development of early-onset obesity and severe insulin resistance in humans with rare variants in KSR2, which affect its functional properties." (PMID 24209692, 2013). "We have shown that mutations associated with human obesity and insulin resistance impair KSR2’s ability to stimulate fatty acid and glucose oxidation, in transfected cells." (PMID 24209692, 2013). "In this study, we found a large number of variants in KSR2 in individuals with severe early-onset obesity." (PMID 24209692, 2013). "Our findings support a major role for hyperphagia as well as reduced metabolic rate in the development of obesity associated with Ksr2 deficiency." (PMID 24209692, 2013). "Mutations in KSR2, a scaffolding protein involved in multiple signaling pathways, lead to severe metabolic alterations that cause early onset obesity in humans." (PMID 24209692, 2013). "Similarly, specific KSR2 mutations in humans with early-onset obesity disrupt ERK pathway activation or hinder AMPK binding." (PMID 41424849, 2026). "Additionally, a recent study carried out in the USA involving 117 youth subjects with early-onset obesity identified 2 individuals with heterozygous KSR2 variants: c.2491C>G (p.Leu831Val) and c.893C>T (p.Thr298Met)." (PMID 39202327, 2024). "Our findings suggest that among this population, KSR2 variants may contribute to an autosomal dominant form of early-onset monogenic obesity." (PMID 39202327, 2024). "Other causes of syndromic obesity include Cohen syndrome, Alström syndrome, X fragile syndrome, Borjeson–Forssman–Lehmann syndrome, 16p11.2 deletion syndrome, kinase suppressor of Ras2 (KSR2) variants, TUB mutations, ACP1, TMEM18, and MYT1L deletion." (PMID 37374323, 2023). "The KSR2 variant identified in this study (Arg554Gln, rs56214831) increases body weight by 0.74 kg/allele and is known to be associated with hyperphagia-induced obesity, low basal metabolic rate and insulin resistance in mice and humans." (PMID 30121879, 2018). "The phenotype of C57BL/6 ksr2−/− mice, including obesity and obesity‐related dysregulation of glucose homeostasis, recapitulates that of humans with KSR2 mutations, demonstrating the applicability of the C57BL/6 ksr2−/− mouse model to the study of the pathogenesis of human disease." (PMID 24997067, 2014).
Obesity (continued). "KSR2 is also mutated in a subpopulation of humans with early onset obesity." (PMID 24997067, 2014). "Other gene mutations in heterozygous states (MRAP2, MC3R, SRC1, KSR2) are associated with obesity and may exhibit autosomal dominant inheritance; however, the clinical phenotype depends on the degree of genetic penetrance and interactions with other genetic and/or environmental factors." (PMID 41751424, 2026). "Since KSR2 genetic polymorphisms are linked to obesity/T2D in humans, our full understanding of how KSR2 differentially regulates general tissue adiposity versus bone marrow adiposity could lead to the identification of novel therapeutic strategies to promote bone health in humans with obesity/T2D." (PMID 36342465, 2022). "While previous studies using global KSR2 knockout mice primarily focused on obesity and systemic metabolic phenotypes, the vascular implications remained unexplored." (PMID 41424849, 2026). "Based on these findings, we propose fivenovel therapeutic candidates aimed at modulating the regulated Ksr2 gene tocounteract obesity induced by a HFD." (PMID 40062973, 2025). "In conclusion, targeting Ksr2 with specific drugs represents a potentialapproach for addressing HFD-induced obesity." (PMID 40062973, 2025). "Specifically, studies involving KSR2 knockout mice have demonstrated the development of obesity, thereby implicating KSR2 in the regulation of energy homeostasis." (PMID 39202327, 2024). "In summary, our investigation of bones in Ksr2 knockout genetic mouse models resulted in the identification of a novel animal model in which the obesity/T2D condition coincides with increased appendicular bone mass." (PMID 36342465, 2022). "In this study, we used a Ksr2 KO genetic mouse model to investigate the relationship between obesity and bone health." (PMID 36342465, 2022). "Combined, these results show that although deletion of Ksr2 leads to obesity with increased bone mass, fracture healing is compromised despite the increased bone accretion observed in unfractured bones." (PMID 36342465, 2022). "Further, deletion of Ksr2 leads to obesity in mice, which suggests that it has a role in energy homeostasis." (PMID 35468812, 2022). "Very interestingly, the elimination of kinase suppressor of Ras 2 (KSR2) in mice, a scaffold protein that coordinates Raf/MEK/ERK signaling pathway, causes insulin resistance and obesity." (PMID 34069890, 2021). "KSR2, a scaffolding protein in the Ras-Raf-MEK-ERK pathway, has been associated with obesity in mice and humans." (PMID 33478395, 2021). "Deletion of KSR2 leads to impair the oxidation of fatty acids and increase their storage as triglycerides, reduced basal metabolic rate thus contributing to obesity and insulin resistance 49,51." (PMID 32210717, 2020). "This raises the possibility that the obesity observed in adult ksr2−/− mice is a consequence of KSR2’s action in the brain or a tissue other than adipocytes." (PMID 27561547, 2016). "Obesity persisted in Ksr 2−/− mice despite being fed the same amount of diet as Ksr2+/+ littermates." (PMID 25825681, 2015). "Disruption of KSR2 in humans and mice decreases metabolic rate and induces obesity, coincident with dysregulation of glucose homeostasis." (PMID 24997067, 2014). "Targeted deletion of ksr2 leads to obesity in mice, suggesting a role in energy homeostasis as highly efficient in conserving energy." (PMID 24410812, 2014). "Ksr2+/− mice also develop obesity when fed on a high-fat diet, indicating that the physiological effects of Ksr2 disruption on energy balance are dosage dependent." (PMID 24209692, 2013). "We explored the role of KSR2 in humans by sequencing 2,101 individuals with severe early-onset obesity and 1,536 controls." (PMID 24209692, 2013). "The therapeuticimpact of camptothecin mimicked the function of the ksr2 gene, suggesting thatsimilar topoisomerase inhibitors may also prevent obesity." (PMID 40062973, 2025).
Obesity (continued). "This suggests that KSR2 exerts opposite effects on leptin and complement factor D/adipsin expression in fat tissues, which is consistent with changes observed in other models of obesity in mice." (PMID 36342465, 2022). "In this study, we set out to investigate whether the deletion of Ksr2, an obesity and T2D gene, bears any effect on bone health, and if so, to evaluate the mechanisms by which KSR2 affects bone metabolism." (PMID 36342465, 2022). "Children who carry certain KSR2 mutations are prone to obesity and type 2 diabetes; mice lacking the gene also develop these conditions due to uncontrolled eating." (PMID 36342465, 2022). "Mutations in human KSR2, MC4R, LEP and LEPR have been described as monogenic causes of obesity, confirming that this screen has relevance to human monogenic obesity disorders." (PMID 30563851, 2018). "Interestingly, these data suggest that MC4R and KSR2 were identified as having a role in common, complex obesity." (PMID 30121879, 2018). "The obesity phenotype caused by brain-specific knockout of KSR2 demonstrates its potent role in cell non-autonomous regulation of energy balance." (PMID 29026529, 2017). "Targeted deletion of Ksr2 leads to obesity in mice, suggesting a role in energy homeostasis." (PMID 24209692, 2013). "Modulation of KSR2-mediated effects may represent a novel therapeutic strategy for obesity and type 2 diabetes." (PMID 24209692, 2013). "The molecular mechanisms regulating KSR2-dependent insulin resistance and obesity are unknown." (PMID 27561547, 2016). "While some of the rare KSR2 variants identified in this study may affect the function of the protein through mechanisms that were not tested here, we show that rare obesity-associated KSR2 mutations disrupt multiple molecular processes when studied in cells." (PMID 24209692, 2013). "Although Ksr2 is expressed in areas of the hypothalamus known to be involved in mediating leptin’s effects on food intake, such as the arcuate nucleus, previous studies performed in Ksr2−/− mice did not convincingly link leptin and melanocortin pathways to the obesity phenotype." (PMID 24209692, 2013). "While to date, other highly penetrant genetic forms of obesity have predominantly been associated with hyperphagia, KSR2 mutations are in addition associated with low BMR and reduced heart rate when tested under the same experimental conditions as individuals with other genetic forms of obesity." (PMID 24209692, 2013). "Although rare loss-of-function variants in KSR2 are highly enriched in cases versus controls, they do not consistently cosegregate with severe obesity and as such are likely to interact with other genetic and/or environmental factors to modulate the phenotype within and between families." (PMID 24209692, 2013). "KSR2-/- mice exhibit decreased AMPK signaling, resulting in defective fatty acid oxidation and triglyceride accumulation, thereby promoting obesity and insulin resistance." (PMID 41424849, 2026). "The interaction between KSR2 and AMPK has been suggested to underpin some of the abnormalities of energy homeostasis and metabolism seen in Ksr2−/− mice, which include obesity, high insulin levels, and impaired glucose tolerance." (PMID 24209692, 2013). "Genes encoding leptin (LEP), leptin receptor (LEPR), melanocortin 4 receptor (MC4R), proprotein convertase subtilisin/kexin type 1 (PCSK1), proopiomelanocortin (POMC), kinase suppressor of ras 2 (KSR2), adenylate cyclase 3 (ADCY3), and others contribute to the development and progression of obesity." (PMID 36141228, 2022). "To formally address whether central hypothalamic KSR2-mediated obesity might also regulate distal limb bone formation nonautonomously, we took a two-pronged approach." (PMID 36342465, 2022). "Interestingly, these genes, with the exception of MC4R, KSR2 and GIPR, have not previously been implicated in obesity, suggesting that key biologic mechanisms underlying obesity have yet to be identified." (PMID 32955435, 2020).